PRKN (parkin RBR E3 ubiquitin protein ligase)
Diseases named in the same sentence as PRKN in open-access papers (continued):
Sharing a sentence is not in itself a finding about the gene and the disease.
Parkinson disease (continued). "For example, in neurodegenerative diseases, there is a significant proportion (>10%) of monogenic families in whom the disease is caused by singular highly penetrant disease genes, e.g., LRRK2 and PRKN in Parkinson’s disease or PSEN1 and APP in Alzheimer ́s disease." (PMID 32854198, 2020). "Treatment with STN DBS for patients with Parkinson disease with LRRK2, GBA, or PRKN mutations appears to be associated with similar motor outcomes but different changes in dopaminergic dose, activities of daily living, motor complications, and cognitive functions." (PMID 30707228, 2019). "Among the 123 patients with Parkinson disease–associated genetic mutations, 80 (65.0%) (27 LRRK2, 30 GBA, 12 homozygous PRKN, and 11 heterozygous PRKN) were included in the meta-analysis for therapy end points, and 7 single cases (5.7%) underwent intraindividual patient analyses." (PMID 30707228, 2019). "Of the 123 patients with Parkinson disease–associated genetic mutations, 115 (93.5%; 46 LRRK2, 33 GBA, 18 homozygous PRKN, and 18 heterozygous PRKN) were included in the meta-analysis for motor end points, and 8 single cases (6.5%) underwent intraindividual patient analyses." (PMID 30707228, 2019). "A fine mapping association study of 43 genes located in the 6q25–q27 region identified several SNPs located within the promoter region shared by two genes—PRKN (formerly PARK2, a well-known early onset Parkinson disease gene) and PACRG—associated with leprosy susceptibility in Vietnamese families." (PMID 30116885, 2018). "Young onset Parkinson's disease may be caused by biallelic mutations in PRKN or other autosomal recessive Parkinson's disease genes, but the majority of patients do not carry known monogenic variants." (PMID 42282179, 2026). "Indeed, three well validated autosomal dominant genes (SNCA, LRRK2, and VPS35) and three well validated autosomal recessive genes PRKN, PINK1, and DJ1 are known to cause Parkinson’s disease, inducing defects in mitochondria, axonal transport, and the dopaminergic system." (PMID 41302176, 2025). "This search identified among our VPSPr cases 1 heterozygous carrier of the recessive PRKN R275W variant, which when homozygous causes juvenile-onset parkinsonism, as well as 1 heterozygous carrier of the GBA N409S variant, a common risk factor for Parkinson disease." (PMID 39711705, 2025). "Additionally, 3-5% of cases can be attributed to monogenic inheritance associated with known Parkinson's disease-related genes, such as SNCA, LRRK2, VPS35, PRKN, PINK1, DJ-1, and GBA, while genetic variants collectively account for 16-36% of the non-monogenic heritable risk." (PMID 38879763, 2024). "Interestingly, almost all clinical cases of PRKN-induced parkinsonism lack Lewy body pathology." (PMID 37468944, 2023). "More than 30 loci are identified as risk factors for PD, some of which are extensively studied, such as mutations in genes encoding synuclein (SNCA), leucine-rich repeat kinase 2 (LRRK2), parkin (PRKN), and Parkinson disease protein 7 (PARK7)." (PMID 35805174, 2022). "Mutations in PRKN are a common cause of autosomal recessive early-onset parkinsonism, however mutations in PINK1 and DJ-1 have also been reported as associated with this type of parkinsonism, although only five causative mutations have been described in the latter." (PMID 18211709, 2008). "USP33 can directly target parkin RBR E3 ubiquitin protein ligase (PRKN), and knockdown of USP33 enhances PRKN-mediated mitophagy, providing a new therapeutic strategy for the treatment of Parkinson's disease." (PMID 40083330, 2025). "We also tested the effect of mutations in pdr-1 and pink-1, the C. elegans homologs of the human PRKN and PINK1 Parkinson’s disease genes, respectively." (PMID 41278705, 2025). "In the PRKN mitophagy model, the prodromal and SWEDD cohorts show higher levels of mitophagy activation than those with parkinsonism." (PMID 39429779, 2024).
Parkinson disease (continued). "In C. elegans and Drosophila, genetic deletion of the ortholog form of human PRKN and PINK1 results in typical Parkinson-like phenotypes." (PMID 37468944, 2023). "Well-established Parkinson’s disease genes include autosomal dominant forms (SNCA, LRRK2, and VPS35) and autosomal recessive forms (PRKN, PINK1 and DJ1)." (PMID 35328025, 2022). "Currently, the best studied mitophagy pathway is regulated by the Parkinson's disease (PD) proteins PTEN Induced Kinase 1 (PINK1) and Parkin (PRKN; PARK2)." (PMID 35642724, 2022). "The mean (SD) age at Parkinson disease onset was 43.4 (3.7) years in LRRK2, 44.7 (4.4) years in GBA, and 28.6 (7.7) years in PRKN carriers." (PMID 30707228, 2019). "This supports the idea that there is a distinct clinical profile of PRKN and PINK1-related Parkinson’s disease." (PMID 31324919, 2019). "Here, we follow up on those results, screening not only LRRK2, but also PRKN, SNCA and PINK1 in a cohort of early-onset and late-onset familial Portuguese Parkinson disease patients." (PMID 18211709, 2008). "Leading examples include Parkin RBR E3 Ubiquitin Protein Ligase (PRKN), PTEN-induced kinase 1 (PINK1) and Parkinson disease protein 7 (PARK7), with robust evidence linking them to the development of PD." (PMID 39456761, 2024). "Systematic review and meta-analysis in which a PubMed search of interventional and noninterventional studies of Parkinson disease with LRRK2, GBA, or PRKN gene mutations published between January 1, 1990, and May 1, 2018, was conducted." (PMID 30707228, 2019). "This increase is mediated by the protein ULK1, suggesting that the process may be independent of PRKN,128 despite higher activation of “PINK1 accumulation” in the simulation for the parkinsonism cohort." (PMID 39429779, 2024).
Parkinsonism (71 papers, 2007 to 2026). Characteristic neurologic anomaly resulting from degeneration of dopamine-generating cells in the substantia nigra, a region of the midbrain, characterized clinically by shaking, rigidity, slowness of movement and difficulty with walking and gait. "EO parkinsonism may greatly benefit from levodopa therapy, such as those with recessively inherited PRKN-associated PD or dominantly inherited LRKK2-associated PD." (PMID 39619277, 2024). "Biallelic variants in DJ-1 (oncogene Dj1, MIM*602533) cause a rare Parkinsonism (PARK7, MIM#606324), the third most common AR PD after the PRKN- and PINK1-related forms, accounting for the 0.4 and 1% of EOPD cases, respectively." (PMID 34630269, 2021). "Early onset LRRK2-related PD as well as milder forms of DNAJC6-related Parkinsonism may present with a phenotype resembling pure PRKN/PINK1 recessive cases." (PMID 34630269, 2021). "In addition to pathogenic mutations in well-established PD-related genes (LRRK2, PRKN, PINK1, SNCA, PLA2G6 and GBA1), we identified pathogenic mutations in genes that have been reported to present as levodopa-responsive parkinsonism but typically present with alternative or atypical phenotypes." (PMID 39420034, 2024).
leprosy (31 papers, 2008 to 2025). Leprosy is a chronic infectious disease affecting primarily the skin and peripheral nervous system. "We replicated the association of PD-linked rare variants in PRKN with T1R in Vietnamese leprosy patients." (PMID 41430073, 2025). "PRKN/PARK2 was identified as a genetic susceptibility factor for leprosy and BU, and was shown to play a role in the degradation of intracellular Salmonella, Mycobacteria and Listeria." (PMID 35846773, 2022). "Our finding of low levels of SOD2 gene expression in skin samples of elderly L-Lep patients is interesting, considering that variants of this gene are located at the same genomic locus as PRKN, a well-known leprosy susceptibility gene." (PMID 33690671, 2021). "In 2004, Mira and coauthors identified polymorphisms in the promoter region shared by PACRG/PRKN genes associated with leprosy per se in Southern Brazilians and Vietnamese." (PMID 32433683, 2020). "First, we focused on the replication of the association of PD-linked genes PRKN and LRRK2 with T1R in Vietnamese leprosy patients." (PMID 41430073, 2025). "In this analysis we included variants associated with leprosy susceptibility at genome-wide significance in other populations, alongside variants at LRRK2 and PRKN, and pathogenic variants at NOD2." (PMID 36121873, 2022). "Here, we investigated whether SNPs located in eleven genes: CCDC122/LACC1, IFNG, IL6, IL10, IL23R, LRRK2, NOD2, PACRG/PRKN, TLR1, TNF and TYK2 are associated to leprosy susceptibility in a population in the North of Brazil." (PMID 32433683, 2020). "Besides the PRKN/PACRG association, a recent study found a new gene located at chromosome 6q25-27—the SOD2 gene—as a risk factor for leprosy susceptibility in two independent Brazilian population samples." (PMID 30116885, 2018). "We first tested if the burden of rare protein-altering variants (defined as minor allele frequency [MAF] < 1%) in PRKN and LRRK2 differed between the 203 T1R-affected vs 200 T1R-free leprosy patients that had not been included in the previous study." (PMID 41430073, 2025).
Dystonia (30 papers, 2013 to 2025). An abnormally increased muscular tone that causes fixed abnormal postures. "These three patients all appear to have young onset PD, with prominent dystonia, resembling similar cases with PRKN and PINK1 mutations." (PMID 33770142, 2021). "Mutations in the PRKN gene can lead to early onset PD, characterized by a clinically typical form of PD that is often associated with dystonia and dyskinesia." (PMID 34281267, 2021). "A case–control study mentioned painful dystonia among three PRKN missense pathogenic carriers and general pain in another missense carrier, while one case report study described painful dystonic posture during off phases in a homozygous exon 3 deletion patient." (PMID 38020640, 2023). "Furthermore, patients with PINK1 mutations have a similar disease course as PRKN mutation carriers, with a good response to L-dopa treatment, but early dystonia and L-dopa induced dyskinesias." (PMID 34281267, 2021). "The motor phenotype of DJ-1 is similar to that of PRKN and PINK1 mutation carriers, including dystonia and L-Dopa-induced dyskinesias." (PMID 40722695, 2025). "Our analysis also uncovered pathogenic or likely pathogenic variants in uncommonly dystonia-associated genes (PCCB, CACNA1A, ALDH5A1, PRKN) in four families where dystonia has been rarely observed in the spectrum of the clinical characteristics so far." (PMID 38458754, 2024). "In a large cohort of 958 PRKN patients, 18% developed dystonia, 15% motor fluctuations, and 68% Levodopa-induced dyskinesias." (PMID 36291241, 2022). "These authors reported how the phenotypic spectrum of patients with variations in PRKN can be highly variable and how sometimes it may start with isolated dystonia, although especially in the lower limbs." (PMID 40141040, 2025). "Dystonia, indeed, may represent an onset sign of PD, especially in PRKN-PD, although some cases of “dystonia gravidarum,” in which dystonia appears in pregnancy and rapidly resolves after delivery, have already been described." (PMID 37658959, 2024). "For example, EOPD with PRKN, PINK1, or DJ-1 mutations are characterized by good response to L-dopa treatment, dystonia and dyskinesia being relatively common, cognitive decline relatively uncommon and a slower deterioration of the disease when compared with idiopathic PD." (PMID 36437996, 2022). "Notably, a case series reported 24% dystonia among the patients but did without specifying whether they were PRKN pathogenic variant carriers." (PMID 38020640, 2023). "The current evidence for PRKN, PINK1 and DJ1 point to a sustained L-dopa response with lower doses, albeit with early motor complications that include dyskinesias and dystonia." (PMID 34281267, 2021). "Pathogenic or likely pathogenic variants were found in four families in genes that are not commonly associated with dystonia (PCCB, CACNA1A, ALDH5A1 and PRKN)." (PMID 38458754, 2024). "A case–control study reported “other symptoms” including pain and dystonia, as an onset symptoms in 43% of PRKN carriers compared to 13% of non-carriers." (PMID 38020640, 2023). "It should be noted that the patient sharing two compound heterozygous deletions in PRKN with a juvenile onset, tremoric phenotype, and dystonia, did not exhibit non-motor symptoms after 35 years of disease duration." (PMID 29163333, 2017).
Onset (25 papers, 2010 to 2025). The age group in which disease manifestations appear. "Mutations in the PRKN gene are the most common genetic cause of early-onset PD and are thought to impair the mitophagy process, a critical mitochondrial quality control pathway." (PMID 39329724, 2024). "Mutations in several genes, including PTEN-induced putative kinase 1 (PINK1) and the parkin gene parkin RBR E3 ubiquitin protein ligase (PARK2), cause autosomal recessive early onset PD in association with the accumulation of misfolded proteins." (PMID 39403921, 2024). "Mutations in parkin (PRKN or PARK2) are the most frequent cause of autosomal recessive PD and account for 10–20% of early-onset PD (age at onset < 40–50 years) in general." (PMID 33468256, 2021). "Mutations in the PRKN gene in humans are the most common cause of autosomal recessive early-onset parkinsonism and reduction on the levels of PRKN expression is linked to late-onset PD." (PMID 32947781, 2020). "Mutations in the PRKN gene are the most common cause of early-onset PD, with a global distribution." (PMID 40722695, 2025). "In addition, PRKN variants are the most common cause of early-onset PD (age of onset ≤ 20 years) accounting for 42% of the familial early-onset PD cases and the majority of PRKN-related PD patients with disease onset before 20 years of age carry bi-allelic PRKN variants." (PMID 38767677, 2024). "Mutations in PRKN and PTEN-Induced Putative Kinase 1 (PINK1) are well-established causes of autosomal recessive early-onset PD." (PMID 31344817, 2019). "In early-onset PD, mutations in six specific genes (SNCA, PRKN, PINK1, DJ1, LRRK2, and GBA) have been reported to account for 16% of cases; these specific mutations are not directly accounted for in our estimate, which is based on a polygenic model." (PMID 21738487, 2011). "Additionally, single heterozygous mutations in PRKN and PINK1 genes are considered minor genetic risk factors for developing PD and single heterozygous substitutions in PRKN gene have been described in sporadic, late-onset PD." (PMID 31737044, 2019).
breast carcinoma (24 papers, 2013 to 2025). "Overall, these findings fit well with other data that deregulated methylation of the PARK2 promoter correlates with PRKN loss in acute leukemia and is associated with poor survival in patients with advanced breast cancer." (PMID 39213189, 2024). "In breast cancer, PRKN targets HIF-1α for ubiquitination, controlling its stability and resulting in metastasis suppression." (PMID 37190124, 2023). "In this regard, miR-218 mediated down-regulation of PRKN could be a potential mechanism that may contribute to apoptosis in breast cancer cells." (PMID 31948106, 2020). "Moreover, endocrine-resistant breast cancer cell lines express elevated parkin RBR E3 ubiquitin protein ligase (PARK2; parkin) protein levels, a protein critical for the induction of mitophagy." (PMID 26157705, 2015). "Specifically, in breast cancer (BRCA) and head and neck squamous cell carcinoma (HNSC), PRKN, PINK1, and MAP1LC3A were downregulated, while SRC and BECN1 were upregulated." (PMID 39859167, 2025). "For example, in breast cancer (BRCA) we found that OPTN, PINK1 and PRKN expression was positively correlated with infiltration of NK cells, while that of BECN1 was negatively correlated with it." (PMID 39859167, 2025). "Finally, we evaluated the physical interaction of SIM2s and PRKN by co-immunoprecipitation and proximity ligation assay (PLA) in SUM159-Sim2s breast cancer cells." (PMID 36966227, 2023).
lung carcinoma (24 papers, 2013 to 2025). "Lung cancer mutated forms of PRKN show impaired mitophagy and reduced cell death after mitophagy induction." (PMID 37190124, 2023). "In addition, PRKN is also involved in cancer regulation and the levels of its mRNA and protein are frequently down-regulated in ovarian and lung cancers." (PMID 31948106, 2020).
glioma (19 papers, 2015 to 2024). A benign or malignant brain and spinal cord tumor that arises from glial cells (astrocytes, oligodendrocytes, ependymal cells). "Located in the 6q25-27 chromosomal region, PRKN is commonly lost/deleted in GBM similar as QKI, and PARKIN protein expression was shown to be downregulated during glioma progression." (PMID 36051438, 2022). "In addition, PRKN inhibits glioma cell growth in vitro and in vivo by downregulating the intracellular levels of β-catenin and EGFR, leading to decreased activation of both Wnt- and EGF-stimulated pathways." (PMID 35832194, 2022).